CASP2 (caspase 2)
Diseases named in the same sentence as CASP2 in open-access papers (continued):
Sharing a sentence is not in itself a finding about the gene and the disease.
cancer (continued). "Several other studies have also demonstrated caspase-2 activation in various types of cancer cells following apoptosis induction by taxanes." (PMID 23672670, 2013). "With regard to other cell types, several studies have demonstrated caspase-2 activation in various types of cancer cells after apoptosis induction by taxanes." (PMID 23672670, 2013). "To test for the presence of casp-2S protein in human cancer cells, we determined the protein expression levels of casp-2L and casp-2S in various cancer cell lines by using this anti-casp-2 antibody." (PMID 23840868, 2013). "The data obtained from MCF7 cancer cells suggested that all the cell death effects of TRIM16 overexpression required the integrity as well as the functional activation of caspase-2." (PMID 23404198, 2013). "Alternatively, cancer cells grown in CM taken from the Surv-T34A cells began to apoptose through a caspase-2- and caspase-9-dependent pathway that was further enhanced by the addition of other chemo- and radiotherapeutic modalities." (PMID 19293795, 2009). "The HUHS015-series of caspase-2 activators may have great potential for developing new treatments for caspase-2-related neurodevelopmental disorders or cancers." (PMID 38676703, 2024). "Herein, we assessed whether the cytotoxic extracts, with established IC50 values, induced apoptosis in cancer cells by analyzing the activity changes in caspase-2, -3, -6, -8, and -9 enzymes in comparison to the control group." (PMID 39861073, 2024). "Furthermore, studies from human cancers have reported that the CASP2 gene located on Ch7q is frequently deleted in hematological malignancies." (PMID 38429264, 2024). "Furthermore, we observed a positive correlation between the content of MDM2 p60 and CASP2 activity in ACP52C resistance in cancer cells." (PMID 37845006, 2023). "Additionally, derivatives of ACP52C conjugated with fatty acid alone or with a CASP2 inhibiting peptide show improved pharmacokinetics and reduced cancer burden, even in ACP52C‐resistant cancers." (PMID 37845006, 2023). "However, apoptosis was inhibited by caspase-2 silencing in HOTAIR knockdown models revealing its significance in inducing apoptosis by targeting HOTAIR in cancer." (PMID 36171196, 2022). "We therefore propose that the phosphorylation state of caspase-2 may predict apoptosis sensitivity and treatment response in cancer." (PMID 32811973, 2021). "It is only through the identification and investigation of additional caspase-2 substrates that we will reveal the cellular processes in which caspase-2 is actively involved, to clarify the important role of this caspase as a safeguard against cancer." (PMID 33425918, 2020).
cancer (continued). "Substrates that contribute to caspase-2’s role in cancer may do so through more indirect mechanisms by regulating transcription or translation." (PMID 33425918, 2020). "Efforts to exploit aneuploidy tolerance mechanisms and the BCL9L/caspase-2/BID axis may limit cancer diversity and evolution." (PMID 28073006, 2017). "The elevated expression of miR-125a-5p and its targeting effect on Casp2 might indirectly explain CASP2' dereliction of duty in cancer." (PMID 26962687, 2016). "Furthermore, an increase in early apoptosis was induced in TRAIL-treated cancer cells under inhibition of either caspase-2 or -9." (PMID 26000607, 2015). "Interestingly, activation of caspase-2 has been reported to activate caspase-8, and sequential activation of caspase-2 and -8 is essential for saikosaponin A-induced apoptosis in human cancer cells." (PMID 25333266, 2014). "Thus, further characterisation of the molecular functions of TRIM16 on caspase-2 was conducted mostly in the MCF7 cancer cells." (PMID 23404198, 2013). "In our previous studies, we demonstrated that caspase-2 was significantly activated (up to 20-fold) along with other caspases (caspase-3, caspase-9 and caspase-8) during apoptosis induction by taxanes in some cancer cells." (PMID 23672670, 2013). "Caspase 2 may protect cells against damage to genetic material and the development of cancer." (PMID 40806590, 2025). "Additional putative caspase-2 substrates may be linked to other potential functions of caspase-2 that may not have an obvious cancer relevance." (PMID 33425918, 2020). "In addition, caspase-2 primes cancer cells for TRAIL-induced apoptosis by processing procaspase-8." (PMID 26000607, 2015). "However, the anti-cancer potential of caspase-2 varied between experimental models." (PMID 27919034, 2014). "Activated the caspase 2-S1P-SREBP1/2 pathway to up-regulate the expression of DHCR7 and FASN in cancer." (PMID 39906741, 2024). "To further investigate this, we profiled a panel of 60 different human cancer cell lines (NCI-60) by immunoblotting and found that 22 of them expressed RAIDD and caspase-2 at a level equal to or greater than that in HeLa cells." (PMID 38676703, 2024). "Several of these genes are involved in pathways that define the hallmarks of cancer, such as VEGFC (lymphangiogenesis), CASP2 (apoptosis and cell stress), and CDC20 (cellular proliferation)." (PMID 30866919, 2019).
cancer (continued). "SRSF3 reportedly modulated the alternative splicing of several apoptosis-related genes, such as caspase-2 (Casp2), programmed cell death 4 (PDCD4), and homeodomain-interacting protein kinase-2 (HIPK2) in distinct cancer cells." (PMID 27983653, 2016). "Growth inhibition of the cancer cells by Super-EBS was prevented by the caspase-2 inhibitor but not by any other cell death pathway inhibitor." (PMID 39781466, 2025). "Caspase-2 depletion alone does not lead to carcinogenesis in mouse models, but caspase-2 provides striking protection against oncogene-driven cancers in animal studies." (PMID 35444189, 2022). "Small interfering RNA-mediated reduction of hnRNP A1 induces apoptosis in human cancer cells but not in normal mortal cell lines, while its high expression has anti-apoptotic effects by regulating splicing of primary caspase-2 transcript." (PMID 28903433, 2017). "We and others have shown that cancer as well as non-cancer cells without functional caspase-2 were more resistant to taxanes." (PMID 25685064, 2015). "Caspase-2 has been suggested to participate in reactive oxygen species-mediated apoptosis, but the precise roles of this “orphan” caspase in cancer cell apoptosis have not been elucidated fully." (PMID 25333266, 2014). "Caspase-2 has been described as an apical caspase as well as a possible executioner caspase, in various types of cancer cells, together with its functions which are independent of apoptosis." (PMID 23672670, 2013). "Furthermore, ROS-induced activation of caspase-2 and depolarization of MMP participate in apigenin and paclitaxel induced cancer cell apoptosis." (PMID 22216199, 2011). "Although there may be a caspase-2-dependent effect in Jurkat T-lymphocytes, this effect has not been observed in MEFs or in various human cancer cell lines." (PMID 38248479, 2024).
cancer (continued). "Hence, assessment of caspase-2 and BID expression levels may help to identify cancers that respond to these therapies." (PMID 39475598, 2024). "Lastly, we demonstrated that the combined treatment of ACP52C with a CASP2 inhibitor could induce cell death in resistant cells and ACP52CGK‐α3, a CASP2 inhibiting peptide‐conjugated ACP52CGK, can reduce the cancer burden even in ACP52C‐resistant cancers in a CDX mouse model." (PMID 37845006, 2023). "It should also be mentioned that the described FRET probe is not suitable for drugs that kill cancer cells through caspase-independent mechanisms or drugs that kill cells through activation of caspases other than caspase 3 or 8, such as caspase 2 mediated apoptosis or necroptosis." (PMID 25188024, 2014). "In the present work, we demonstrated that apigenin could sensitize cancer cells to paclitaxel induced apoptosis through suppressing SOD activity and leading to accumulation of ROS and cleavage of caspase-2, suggesting the combined use of apigenin and paclitaxel was effective for cancer therapy." (PMID 22216199, 2011). "However, it remains possible that not all aspects of Caspase-2 biology are conserved between mice and humans, as previously also recognized for the Caspase-2-dependent Chk1-suppressed cell death pathway that appears functional in human cancer cells but not in mouse lymphocytes or MEF." (PMID 25857265, 2015). "Caspase-2 has been referred to as an “orphan” caspase, and its role in TRAIL-induced apoptosis of cancer cells has not been established fully." (PMID 26000607, 2015). "Also, mRNA expression of the cancer stem cell (CSC) markers CD90 (Thy1) and CD133 (Prom1) was not substantially different between wt and Casp2−/− liver tumors (Fig EV2C)." (PMID 33225610, 2020). "Although a role for CASP2 in DRGN apoptosis has not been identified, CASP2 does mediate apoptosis in hippocampal neurons, sympathetic neurons, retinal ganglion cells, pancreatic acinar cells and insulin secreting (HIT-T15) cells, cancer cells and murine macrophages." (PMID 23451279, 2013).
infection (21 papers, 2009 to 2025). The state of being infected such as from the introduction of a foreign agent such as serum, vaccine, antigenic substance or organism. "Because many other caspase family members have been implicated during the immune response to infection, perhaps the evolved function of caspase-2 is also to protect cells from intracellular infection." (PMID 38248479, 2024). "Although several other caspase family members have been well-studied and shown to defend against intracellular infection, fewer studies have investigated the role of caspase-2 during in vivo infection." (PMID 38248479, 2024). "Concomitantly, the host expressed as many as 16 different caspase-2 isoforms throughout the infection cycle." (PMID 39242818, 2024). "We also explore and review several stimuli published in the caspase-2 field, test ferroptosis-inducing stimuli, and study in vivo infection models." (PMID 38248479, 2024). "Of the three caspase genes, caspase-1 was upregulated at day 2 compared to day 5 and caspase-2 was upregulated at day 3 compared to day 7 infection, however, in both cases the changes in gene expression were relatively minor." (PMID 33424791, 2020). "For Casp2, the number of linkages increased significantly during secondary infection relative to the number during primary infection." (PMID 25341656, 2014). "The gene for caspase 2 was expressed in HEp-2 cells inoculated with isolates 34, 37, 174 and 82; a higher expression was detected at 24 hours of infection." (PMID 25299837, 2014). "Previous work indicated that smooth virulent Brucella app downregulates Casp2 transcriptional levels at an early stage of infection and inhibition of Casp2 activity also increased the number of rough Brucella abortus surviving inside macrophages." (PMID 22216095, 2011). "Our previous microarray study indicates smooth virulent B. melitensis strain 16 M down-regulates caspase-2 transcriptional levels and inhibits transcription of genes involving mitochondria activities at an early stage of infection." (PMID 19714247, 2009). "Notwithstanding all of these potential connections, the fields of metabolism, redox homeostasis, mitosis, apoptosis, and infection are all complicated in their own regard; the study of them altogether, in the context of caspase-2, will surely be a monumental task." (PMID 38248479, 2024). "It is likely that intracellular pathogens with similar lifestyles to Brucella (e.g., Salmonella, Mycobacterium, Listeria, Francisella, and Legionella) may utilize caspase-2 during infection." (PMID 24350060, 2013). "In addition to infection, we found that caspase-2 also mediated cell death as well as caspase-3 and -8 activation in macrophages treated with etoposide, naphthalene, and anti-Fas." (PMID 24350060, 2013). "Caspase-2 plays important biological roles from oocyte development to aging control, and in intermediary development stages including DNA damage repair, tumor prevention, and infection control." (PMID 24350060, 2013). "We hypothesized that caspase-2 is required to mediate cytokine production, maturation and activation, and antigen presentation of DCs after infection with RB51, leading to Brucella-specific T cell priming." (PMID 22927979, 2012). "However, caspase-2 has been found critical to many biological processes including DNA damage repair, tumor prevention, immune responses to pathogen infections, and aging controls." (PMID 22927979, 2012). "Some proapoptotic molecules, including cyc1 (cyto c), caspase-2 (Casp2), Txnip and Casp7, Cebpb, Eaf2, were significantly down-/upregulated after infection with Brucella, and this could result in apoptosis of infected cells." (PMID 22216095, 2011). "The caspase-2 specific inhibitor (Z-VDVAD-FMK) blocked macrophage cell death caused by RB51 or RA1 98.2 %±0.5% or 80.3%±5.2%, respectively, compared to untreated controls at 24 h post infection." (PMID 19714247, 2009). "This confirmed that the activation of caspase-2 occurs at the early stage of infection." (PMID 19714247, 2009).